TLR4 (toll like receptor 4)
Diseases named in the same sentence as TLR4 in open-access papers (continued):
Sharing a sentence is not in itself a finding about the gene and the disease.
Sepsis (continued). "Blocking the TLR4 pathway with TAK242 could improve heart dysfunction and myocardial damage in sepsis." (PMID 35891967, 2022). "Absence of TLR2 and TLR4 improved cardiac function after ischemia/reperfusion (I/R) injury and during sepsis in mice and ameliorated impaired cardiac calcium handling in presence of extracellular histones." (PMID 36131923, 2022). "In the LPS-induced model of SAKI, it has been demonstrated that the suppression of abnormal immune responses through inhibition of the TLR4/NF-κB pathway might prevent AKI and improve the clinical outcome of sepsis." (PMID 36010680, 2022). "Therefore, we further verified the mRNA level of LPIN1 after LPS stimulation and found its expression reduced in the sepsis rat model along with NR8383 and RLE cell lines, which were together with increased TNFα and TLR4 expression." (PMID 35222395, 2022). "Disfunction of neutrophils in sepsis has been described in previous studies, however, little is known about the role of microRNA-let-7b (miR-let-7b), toll-like receptor 4 (TLR4), and nuclear factor kappa B (NF-κB) activity in neutrophils and how they participate in the development of sepsis." (PMID 33868293, 2021). "Upregulated TLR4 and Myeloid Differentiation Primary Response 88 (MYD88) protein were demonstrated along with progranulin activation in our RT-qPCR-confirmed molecular network of the early antimicrobial response to sepsis." (PMID 34476621, 2021). "Shikonin could alleviated sepsis- induced ALI by increasing the levels of miRA-140-5p and decreasing the levels of TLR4." (PMID 34956235, 2021). "Despite a lack of larger studies demonstrating an association between TLR4 and biomarkers like PCT and CRP in diagnosis of sepsis, results of a recent study conclude the possibility of using TLR2 and TLR4 expression to determine the severity of sepsis as a diagnostic biomarker (p < 0.05)." (PMID 33803628, 2021). "Collectively, using human lung EC, as well as a sterile sepsis model in neonatal mice, we demonstrate that FOXC2 regulates its own expression through a histone acetylation- dependent positive feedback loop during TLR4 stimulation in developing lung EC." (PMID 34017833, 2021). "In mice, the predominant TLR of B cells is TLR4, which plays a critical role in the innate immune response against Gram-negative bacteria by recognizing the sepsis-inducing bacterial endotoxin lipopolysaccharide (LPS)." (PMID 34543116, 2021). "A lot of therapeutic agents have been developed to treat sepsis, including antibodies against LPS, antitumor necrosis factor (TNF) agents, Toll-like receptor 4 (TLR4) antagonists, drugs targeting the coagulation cascade, and drugs targeting platelet-activating factor (PAF)." (PMID 33946374, 2021). "Animal death caused by sepsis in response to intravenous injection of PAMP from E. coli was attenuated in mice with Casp1, Casp1/11, and Gsdmd depletion but not in Tlr4–/–, Casp11–/– mice or mice lacking receptors for IL-1B (Il1r–/–) and IL-18 (Il18r–/–)." (PMID 34858408, 2021). "The expressions of TLR2, TLR3, TLR4, and TLR7 increased in the kidneys and intestine of sepsis mice, indicating that these four cytokines could influence the effect of pro-inflammatory response during infection." (PMID 34938184, 2021). "TLR4 plays a role in LPS and HMGB1-induced apoptosis in PBMCs of patients with sepsis." (PMID 34733114, 2021). "According to some literatures on NAFLD, some immune-related loci associated with NAFLD could exhibit some level of pleiotropy influencing sepsis with genes of CD14, IL-6, MIF, TLR4, and TNF." (PMID 34938184, 2021). "Moreover, many approaches have developed TLR4 antagonists such as TAK-242 (CLI-095), which have advanced to block TLR4 signaling in various diseases such as sepsis, septic shock, rheumatoid arthritis, and lung inflammation." (PMID 33673673, 2021).
Sepsis (continued). "Stimulated peripheral blood mononuclear cells (PBMCs) with or without lipopolysaccharides (LPS) and high-mobility group box 1 (HMGB1) were cultured with or without TLR4 inhibition using monoclonal antibodies from 20 patients with sepsis." (PMID 34733114, 2021). "In sum, the activation of TLR2, TLR4, TLR7, TLR9 and NLRP3 are almost certainly maintained by DAMPs in severe COVID-19, ALI/ARDS and sepsis and may need to be therapeutically addressed." (PMID 33672738, 2021). "One such unsuccessful therapeutic is TAK-242, a small-molecule inhibitor of TLR4 signaling, that failed to suppress cytokine levels in patients with sepsis or respiratory failure in a phase III study." (PMID 33841413, 2021). "Our study is the first to demonstrate that TLR4 inhibition increased the cell death of stimulated PBMCs in patients with sepsis and this increased cell death was not via TNF/TNF receptor-mediated apoptotic pathway." (PMID 34733114, 2021). "The LPS-MD-2/TLR4 antagonist, eritoran, also failed to reduce mortality among patients with severe sepsis." (PMID 33841413, 2021). "In addition, hepatocyte-specific deletion or pharmaceutical inhibition of toll-like receptor 4 (TLR4), a master regulator of cellular inflammation to which LPS binds, attenuates liver injury following sepsis." (PMID 33816466, 2021). "TLR4 mediates B‐cell recognition of lipopolysaccharide (LPS), a membrane constituent of Gram‐negative bacteria that drives the inflammatory response in sepsis." (PMID 34369652, 2021). "In sepsis, the activation of the MAPK pathway might result from aberrant upstream signaling, such as TLR4." (PMID 32908632, 2020). "TLR4 excessive activation by a Gram-negative bacteria lipopolysaccharide (LPS) leads to sepsis, while TLR4 stimulation by DAMPs is a common mechanism in several inflammatory and autoimmune diseases." (PMID 32765484, 2020). "In the present study, we focused on the effects of TLR4 blockade on muscle wasting and muscle function in sepsis, which the clinical trials did not examine." (PMID 31959927, 2020). "On the other hand, TLR4 inhibition is a therapeutic approach to Gram-negative and sterile sepsis as well as autoimmune inflammatory pathologies such as atherosclerosis, rheumatoid arthritis, or hemorrhagic shock." (PMID 32765484, 2020). "Since TLR4 is universally expressed in most, if not all, cells, we next accessed the direct anti-sepsis effect of puerarin on hepatocytes." (PMID 32457606, 2020). "The TLR4 inhibitors, eritoran, polyamidoamine, and tak-242, have been shown to decrease the inflammatory response in sepsis animals, and the NLRP3 inhibitor, MCC950, has been shown to have a positive effect in sepsis mice." (PMID 33324236, 2020). "The most well-characterized sepsis-inducing factor is lipopolysaccharide (LPS), the cell wall constituent of Gram-negative bacteria, activates Toll-like receptor 4 (a member of pattern recognition receptors)." (PMID 32079307, 2020). "Both the in vivo and the in vitro data suggest that the GSS has anti‐apoptotic effects on LPS‐induced lung vascular EC injury via TLR4/ Myd88/NF‐κB/BCL‐2 signalling, which may be the main reason why GSS effectively alleviates sepsis‐induced ALI." (PMID 31756053, 2020). "Silence of NEAT1 suppressed LPS-induced inflammatory response of macrophages by mediating miR-17-5p and TLR4, indicating that NEAT1 might be a promising target for sepsis treatment." (PMID 32099901, 2020). "Our data suggested that QX1 may represent a novel therapeutic strategy for sepsis by suppressing the activity of calcium, MAPK, and TLR4/NF-κB pathways, but promoting the activation of AKT, thus controlling cytokine storm and regulating immune balance." (PMID 32908632, 2020). "However, NET formation was shown to be ROS(NOX)-independent in multiple settings including sepsis, and so was NET release induced by complement receptors, TLR2/TLR4 ligands or TLR4-activated platelets." (PMID 32010131, 2019).
Sepsis (continued). "The modulation of the TLR4 pathway can mitigate the injury from Gram-negative bacteria-induced sepsis." (PMID 31847111, 2019). "Thereby, TLR4 and TLR2 mRNAs are highly expressed in patients with sepsis." (PMID 31671729, 2019). "In patients with neutropenic fever, levels of mRNA expression of TLR2 and TLR4 were significantly higher in sepsis patients compared to patients without sepsis." (PMID 30796468, 2019). "Despite pre-clinical evidence, TLR4 modulation has not been able to alter the inflammatory cascade in humans with sepsis." (PMID 31491842, 2019). "In addition, we indicated that the upregulation of TLR4 in the CD38−/− mice is able to promote the production of IFN-γ, thus enhancing inflammatory reactions which ultimately leads to aggravated sepsis." (PMID 30915370, 2019). "LPS, released from Gram-negative bacteria, stimulates cells by activating TLR4-mediated signaling to induce inflammatory cytokine and nitric oxide release, leading to sepsis." (PMID 31581682, 2019). "Our results suggested that the increase of TLR4 expression in CD38−/− mice might be able to promote the production of IFN-γ, which contributes to more severe kidney injury in sepsis induced by LPS." (PMID 30915370, 2019). "After LPS interacts with specific receptors such as Toll-like receptor 4 (TLR-4) on host immune cells, inflammatory cytokines like IL-1, TNF-α, and IL-6 are secreted, leading to hemodynamic alteration, widespread inflammation, and sepsis." (PMID 29515089, 2018). "TLR-4 forms a homodimer and recognizes LPS produced by Gram-negative bacteria, e.g., in cases of sepsis." (PMID 30301191, 2018). "As a synthetic ALX agonist, BML-111 could mitigate inflammatory response in the lung and intestinal mucosal barrier during sepsis by inhibiting the activation of the Akt, ERK1/2, and p38 MAPK signaling pathways and decreasing the expression of TLR2 and TLR4." (PMID 30186119, 2018). "These significant increases in TLR4 and Hsp expression indicate that over the period studied, the “immune paralysis” phase of sepsis was not reached." (PMID 29795607, 2018). "Instead, having a functional capacity to respond to LPS with TLR4—the sensing and effector pathway triggered by invasive gram-negative bacteria—is likely to be a functional trait in sepsis." (PMID 30158480, 2018). "Previous data showed that blocking TLR4 signaling with an MD2-TLR4 antagonist had no clear beneficial effects in sepsis, when compared to placebo." (PMID 29760586, 2018). "Thus, researchers have focused on TLR4/MEK/ERK/TNF-α signaling, with the aim of developing a method to prevent mitochondrial dysfunction and AKI induced by sepsis." (PMID 30092777, 2018). "Eritoran (E5564) is a specific TLR4 antagonist initially purposed for the treatment of sepsis, but a failed a phase III clinical trial due to improved patient care in the placebo group prevented its eventual use in sepsis treatment." (PMID 30042762, 2018). "Targeting myeloid differentiation protein 2 (MD-2) or Toll-like receptor 4 (TLR4) with small molecule inhibitor rescues the systemic inflammatory response syndrome (SIRS) in sepsis due to infection with Gram-negative bacteria but not other microbes." (PMID 28145460, 2017). "TLR4, the most widely examined TLR, is a member of the TLR family and the receptor complex that mediates hyper-inflammatory response and contributes to high mortality during endotoxin shock and severe sepsis." (PMID 28976997, 2017). "The rise in the number of CD11chiCD4+ pDCs in the bone marrow during sepsis was dependent on signaling through MyD88, but not on TLR4." (PMID 29218051, 2017). "In addition, the release of CIRP during sepsis is capable of initiating adaptive immune response by directly activating CD4+ and CD8+ T cells in TLR4-depentent manner in the spleen." (PMID 29134130, 2017).
Sepsis (continued). "Nonetheless, the magnitudes of these LPS-stimulated changes were not different between variant and wild-type TLR4+896A/G or CD14-159C/T allele carriers as well as between non-severe sepsis and severe sepsis cases." (PMID 27861595, 2016). "In comparison with healthy controls, higher frequencies of TLR4+896A/G and CD14-159C/T variant alleles were noted among severe sepsis and non-severe sepsis febrile de-compensated cirrhotic patients as well as afebrile compensated cirrhotic patients." (PMID 27861595, 2016). "Among cultured CD16- monocytes collected from cases carrying wild-type TLR4+896A/G or CD14-159C/T allele and non-severe sepsis, acute LPS incubation significantly stimulated HLA-DR/mCD14 expressions and phagocytosis." (PMID 27861595, 2016). "Upregulation of TLR2 and TLR4 in response to the presence of PAMPs has extensively been studied in non-sterile inflammatory conditions like sepsis and septic shock." (PMID 27260481, 2016). "In a large clinical trial the TLR-4 antagonist eritoran did not, however, improve outcome in patients with severe sepsis or septic shock (±80 % on mechanical ventilation)." (PMID 27091359, 2016). "Collectively these data suggest that WISP1-αvβ3 integrin signaling is involved in TLR4 pathways in macrophages and may be an important contributor to TLR4/CD14 mediated inflammation in sepsis induced lung injury." (PMID 27349568, 2016). "The baseline and LPS-stimulated TLR4 expression on the CD16- (classical) monocytes were not different between variant and wild-type allele carriers of TLR4+896A/G or CD14-159C/T as well as between non-severe sepsis and severe sepsis cases (data not shown)." (PMID 27861595, 2016). "In febrile acute de-compensated cirrhotic patients, TLR4+896A/G and CD14-159C/T polymorphisms-related non-classical and classical monocytes dysfunction resulted in increased severe sepsis risk." (PMID 27861595, 2016). "In comparison with non-severe sepsis cases, higher frequencies of TLR4+896A/G and CD14-159C/T variant alleles were noted in severe sepsis cases." (PMID 27861595, 2016). "Among both TLR4+896A/G and CD14-159C/T variant allele carriers with severe sepsis, a significant negative correlation was found between plasma endotoxin level and LPS-stimulated HLA-DR expression on CD16- monocyte." (PMID 27861595, 2016). "Our data demonstrate that n-3 PUFA intervention can suppress LPS-induced inflammation and weight loss via, at least in part, down-regulation of pro-inflammatory targets of the TLR4 signaling pathway, and highlight the therapeutic potential of n-3 PUFA in the management of sepsis." (PMID 25689565, 2015). "Contrary to TLR2- or TLR4-deficient mice, mice which are deficient in Myd88, a signalling module shared by many TLR receptors, failed to deal with mild or moderate sepsis and succumbed rapidly to infection." (PMID 26147469, 2015). "A well-known sepsis-inducing factor is the membrane constituent of Gram-negative bacteria, lipopolysaccharide (LPS), signalling via Toll-like receptor-4." (PMID 26390973, 2015). "Our findings provide clues to develop new peptide-based drugs to target Pellino-1 protein in TLR4 signaling pathway for the treatment of sepsis." (PMID 25766838, 2015). "From a molecular view, role of Toll-like receptor 4 (TLR4) in microglial activation was proposed in several stressor conditions, for instance in ischemia-reperfusion injury, chronic alcohol consumption and sepsis." (PMID 25811788, 2015). "Based on these findings together with our results, it is possible that TLR3 or TLR4 activation increases IFN-β1, which subsequently increases TRAIL in CD8+ regulatory T cells during sepsis, finally contributing to the immunosuppressive state of sepsis." (PMID 25766838, 2015). "Interestingly, in our models, the expression of TLR4 was upregulated on both CD34+ CD38− and CD34+ CD38+ cells and this is in contrast to modulation of those receptors on monocytes from patients with sepsis." (PMID 26272069, 2015).
Sepsis (continued). "Our group and others have shown that blockade of TLR2 or TLR4 was successful in decreasing disease severity in sepsis models of Gram-negative and-positive bacteria, respectively." (PMID 26147469, 2015). "In the present study, we tested the hypothesis that pharmacological inhibition of Toll-like receptor 4 (TLR4) would improve renal function and reduce renal damage in experimental sepsis, even after AKI had already developed." (PMID 25182709, 2014). "The current study presents the dynamics of the TLR4 and JAK/STAT signalling pathway by updating our previous study with new interactions and entities to gain an insight into a different pathological condition of sepsis." (PMID 25255432, 2014). "In spite of the potential of these and other LPS and/or TLR4 antagonists in vitro and in Phase I and II clinical trials, none of them have been shown to be effective for sepsis therapy, and new strategies should be evaluated." (PMID 25056632, 2014). "Among the patients with neutropenic fever, the mRNA expression of TLR2 and TLR4 was significantly higher in septic patients than in patients without sepsis symptoms." (PMID 25412934, 2014). "Numerous studies have indicated that LPS triggers pathogenesis of sepsis by recognizing TLR4 (Toll-like receptor 4) and CD14 on the surface of cells; so an effective way to prevent sepsis could be by neutralizating LPS." (PMID 24654965, 2014). "In patients with neutropenic fever, the mRNA expression of TLR2 and TLR4 was significant higher in septic patients than in patients without sepsis symptoms (ΔCt TLR2 0.93 ± 0.82 vs 0.78 ± 0.85 and ΔCt TLR4 0.38 ± 0.29 vs 0.34 ± 0.25)." (PMID 25412934, 2014). "We demonstrate that the mRNA expression of TLR2 and TLR4 before induction chemotherapy was significantly higher in septic patients than in patients without sepsis symptoms." (PMID 25412934, 2014). "In order to study the mechanism of sepsis at cellular level, we evaluated the qualitative roles of TLR4 and JAK/STAT signalling with their negative and positive feedback loops necessary to produce effective immune response." (PMID 25255432, 2014). "Moreover, the absence of significant associations in meta-analysis data for periodontitis, tuberculosis, meningococcal disease and sepsis, signifies that the functional alterations related to polymorphic TLR4 variants may not be critical to produce the clinical phenotype." (PMID 24282567, 2013). "During a gram-negative infection, TLR-4 recognizes endotoxin and originates a systemic inflammatory response in sepsis with potentially fatal effects in hosts." (PMID 24249974, 2013). "CEACAM1 is also reported to inhibit Toll-like Receptor-2 signaling and Toll-like Receptor-4, thus increased circulating soluble CEACAM1 might contribute to inhibition of Toll-like Receptor responses in sepsis." (PMID 23894299, 2013). "To date, TLR2 and TLR4 expression has been mainly studied in monocytes, and most studies show enhanced surface expression of TLR2 in sepsis, while the data concerning TLR2 surface expression in trauma and SIRS patients or TLR4 expression are more controversial." (PMID 23098236, 2012). "Two TLR4 antagonists, E5564 (Eritoran) by Eisai, Inc., and TAK-242 by Takeda Pharmaceutical Company, have been used in phase III clinical trials for the management of severe sepsis where the drugs ware largely well tolerated." (PMID 22577589, 2012). "The role of TLR4 in human patients with sepsis, but also in non-infectious diseases, such as inflammatory bowel disease and rheumatoid arthritis, were studied." (PMID 23016675, 2012). "Thus, we showed that the innate immunity receptors TLR2 and TLR4 and the adapter protein MyD88 are important in the development of AKI secondary to sepsis." (PMID 22655058, 2012). "As far as sepsis and bacterial recognition is concerned, TLR4 seems to be the central sensor of Gram-negative bacterial products, whereas TLR2 seems to be the key receptor in activating the immune system against Gram-positive bacteria." (PMID 21765613, 2011).